HPSE (heparanase)
Diseases named in the same sentence as HPSE in open-access papers (continued):
Sharing a sentence is not in itself a finding about the gene and the disease.
Sepsis (continued). "Schmidt and colleagues studied in a model of sepsis-induced renal and pulmonary injury the potential of nonanticoagulant N-desulfated re-N-acetylated heparin (NAH) as a competitive heparanase inhibitor." (PMID 27699168, 2016). "We induced polymicrobial sepsis in mice using cecal ligation and puncture (CLP) in the presence or absence of competitive heparanase inhibitors (heparin or nonanticoagulant N-desulfated re-N-acetylated heparin [NAH])." (PMID 24400155, 2013).
melanoma (42 papers, 2009 to 2025). A malignant, usually aggressive tumor composed of atypical, neoplastic melanocytes. "The elevated expression of heparanase (HPSE) in melanoma cells has also been associated with increased cell growth, angiogenesis, and metastasis to the brain." (PMID 33466236, 2021). "However, in a sub group of 46 patients diagnosed as stage IVc melanoma, strong heparanase staining was associated with reduced survival rates [hazard ratio=2.1; 95%CI 1.1-4.1, p=0.025]." (PMID 27732945, 2016). "Furthermore, heparanase gene silencing was associated with reduced Erk phosphorylation and cytokine expression, thought to play an essential role in melanoma progression." (PMID 27732945, 2016). "Importantly, in stage IVc melanoma patients, high levels of heparanase were associated with poor prognosis (p=0.02)." (PMID 27732945, 2016). "Likewise, high levels of heparanase in melanoma patients were associated with poor prognosis." (PMID 27732945, 2016). "Another preclinical study demonstrated a 29-fold increase in heparanase expression in metastatic melanoma samples compared to normal tissue, highlighting its selective localization in vascularized malignant areas." (PMID 39594665, 2024). "Strong inhibitory effect on heparanase activity in melanoma cells; demonstration of reduced invasiveness in reconstructed basal membranes." (PMID 39594665, 2024). "In preclinical models, suramin (polysulfonated naphthylurea) has been shown to have a strong inhibitory effect on heparanase activity in B16 melanoma cells and their subsequent invasiveness in reconstructed basal membranes." (PMID 39594665, 2024). "HPSE expression is increased in brain metastatic melanoma cells, and experiments using an in vivo brain model show that HPSE-1 expression increases melanoma cell invasion into the brain." (PMID 37190188, 2023). "Aiming to investigate this, we depleted HSPGs by downregulating Exostosin 1 (EXT1), a key enzyme in HS formation, or upregulating heparanase in human MV3 human melanoma cells, and investigated their response to cytotoxic drugs." (PMID 36982528, 2023). "Experiments with different cancer cell lines and tumor models (e.g., lymphoma, melanoma, urothelial cells), in which heparanase-1 expression was downregulated by RNA interference, showed reduced invasion or adhesion, and increased apoptosis." (PMID 36680276, 2023). "Of these, VEGF was shown to act differentially depending on the setting: reducing heparanase expression in endothelial cells and increasing heparanase expression in melanoma cells." (PMID 34681753, 2021). "Heparanase gene expression was increased in Snail-B16F1 melanoma cells as compared to the control Mock-B16F1." (PMID 33917849, 2021). "This was found to be the case in melanoma cells subjected to siRNA mediated knock-down of heparanase expression." (PMID 31850210, 2019). "Using melanoma cells that express a high level of endogenous heparanase, we demonstrates that heparanase regulates a number of genes involved in a substantial set of biological functions." (PMID 31044520, 2019). "To characterize the subcellular location of heparanase in the melanoma cells, we performed cell fractionation to separate cell lysates into cytosolic, nuclear and nuclear binding protein fractions." (PMID 31044520, 2019). "In this study, siRNA mediated silencing of HPSE expression in melanoma cells induced significantly increased expression of an array of genes classified as GO terms of positive regulation of cell death and apoptotic process." (PMID 31044520, 2019). "They found when poorly metastatic murine melanoma and T-lymphoma cells were transfected with the heparanase gene, this resulted in a massive increase in metastases." (PMID 31850210, 2019). "The pro‐apoptotic gene expression and observation of apoptosis were extended to another melanoma cell line, MV3 cells, thus consolidating the anti‐apoptosis effect of heparanase in melanoma cells." (PMID 31044520, 2019).
melanoma (continued). "By silencing the heparanase gene (HPSE) in MDA‐MB‐435s melanoma cells, we investigated the impact of this protein on gene transcription." (PMID 31044520, 2019). "The MAPK pathway has been reported to be involved in regulating the biological effect of HPSE in tumor cells such as nasopharyngeal carcinoma and melanoma." (PMID 29849826, 2018). "Neurotrophins seem to promote melanoma cell invasion by stimulating and sustaining growth and migration, for example, by inducing the expression of heparanase or cytoskeletal rearrangements." (PMID 28298807, 2017). "Paraffin sections from 69 metastatic melanomas were subjected to immunohistochemical analysis, applying anti-heparanase antibody." (PMID 27732945, 2016). "In order to examine heparanase levels in metastatic melanoma, 69 pathological samples from patients with melanoma metastases were subjected to immunostaining applying anti-heparanase antibody." (PMID 27732945, 2016). "Utilizing immunohistochemistry, we found that most (88%) melanoma metastases stained positive for heparanase." (PMID 27732945, 2016). "In pre-clinical studies, heparanase gene silencing in melanoma cells resulted in smaller tumors and decreased lung metastasis, associating with reduced cellular invasion, migration and adhesion." (PMID 27732945, 2016). "While heparanase is reported to be induced in melanoma and to correlate with poor prognosis, a systematic evaluation of its expression in metastatic lesions has not been sufficiently investigated." (PMID 27732945, 2016). "Heparanase is highly expressed in metastatic melanoma and predicts poor survival of stage IVc melanoma patients, justifying the development and implementation of heparanase inhibitors as anti-cancer therapeutics." (PMID 27732945, 2016). "Taken together, we describe for the first time a systematic examination of heparanase expression and clinical significance in melanoma metastases." (PMID 27732945, 2016). "Accordingly, heparanase inhibitors are presently evaluated clinically in melanoma patients among other indications." (PMID 27732945, 2016). "Heparanase expression is induced in many types of cancers, including melanoma, and promotes tumor growth, angiogenesis and metastasis." (PMID 27732945, 2016). "Immunofluorescent staining confirmed that T-cadherin overexpression in melanoma clone culture resulted in the reduced expression of Tie 1 and increased expression of heparanase." (PMID 26197340, 2015). "Astrocytes also produce heparanase, which was shown to contribute to the brain-metastatic specificity of melanoma cells, and MMP-9, which can support invasion of tumor cells and release growth factors from the extracellular matrix." (PMID 23344048, 2013). "Heparanase secreted from melanoma cells cleaves heparan sulphate (HS), degrading this barrier that is normally protective of the basement membrane's underlying type IV collagen structure from proteolysis." (PMID 22720169, 2012). "Melanoma cells also produce heparanase disrupting the basement membrane facilitating tumour cell invasion." (PMID 22720169, 2012). "Recently, a novel G protein-coupled receptor, GPR56, which inhibits VEGF production from the melanoma cell lines, as well as heparanase, which induces VEGF, were reported as possible tumor targets for influencing VGEF expression." (PMID 22442699, 2012). "Supra-additive levels of heparanase activity are found when brain endothelial cells are coincubated with brain-metastatical melanoma cells in equicellular amounts." (PMID 22084751, 2011). "In brain-metastatic melanoma cells, NTs can promote invasion by enhancing the production of extracellular matrix degradative enzymes such as heparanase, an enzyme capable of locally destroying both the extracellular matrix and the basement membrane of the BBB." (PMID 22084751, 2011). "Astrocytes are supposed to contribute to the brain-metastatic specifity of melanoma cells by producing NTs-regulated heparanase." (PMID 22084751, 2011).
melanoma (continued). "One of the many features of the malignant melanoma phenotype, in vitro and in vivo, is the elevated heparanase production and activity, which confers the capacity of degrading the subendothelial matrix produced by endothelial cell monolayer cultures." (PMID 22084751, 2011). "Heparanase expression has been found upregulated in gastric, pancreatic, melanoma, prostate and bladder cancers." (PMID 19878561, 2009). "However, in some combinations with antitumor drugs, heparanase inhibitors can improve clinical outcome, making their potential use as adjuvants in the therapy of melanoma and other malignancies possible." (PMID 39594665, 2024). "Indeed, the metastatic potential of highly invasive melanoma cells to extravasate and successfully colonize the lung was related to the capacity of heparanase-1 to degrade HS in the walls of pulmonary blood vessels." (PMID 36680276, 2023). "Furthermore, EGR-1 has been described to act as a transcriptional repressor in melanoma cells and as an activator in breast, colon, and prostate cancer cells of the heparanase gene." (PMID 35409280, 2022). "As well as inhibiting heparanase enzymatic activity a selected glycopolymer was further tested in in vitro invasion and migration assays using the murine B16 melanoma line; activities which may be attributed to heparanase." (PMID 31850210, 2019). "In addition to heparanase overexpression, melanoma cells were reported to exhibit 3-O-sulfotransferase gene hypermethylation and subsequent gene silencing." (PMID 32010611, 2019). "Recently, we reported that most melanoma metastases are stained positive for heparanase." (PMID 29464068, 2018). "Moreover, we found that in stage IVc melanoma patients, high heparanase expression in the metastases predicts poorer prognosis, clearly implying that heparanase levels in the metastatic lesions affect the disease outcome." (PMID 29464068, 2018). "Furthermore, neurotrophins were discussed to augment the production of heparanase, an important and unique extracellular matrix degradative enzyme in brain metastasis of melanoma cells." (PMID 27901477, 2017). "Notably, in stage IVc melanoma patients, high levels of heparanase correlated with shorter survival rates." (PMID 27732945, 2016). "Besides tumor cells, astrocytes were found to produce heparanase as well, significantly contributing to the brain colonization of melanoma cells." (PMID 23344048, 2013). "Several melanoma cell lines degrade ECM through heparanase enzyme degradation and pathological specimens of melanoma tissue demonstrate increased levels of heparanase mRNA at all stages of tumour development, with highest expression found in vertical growth phase samples." (PMID 22720169, 2012). "In conclusion, we demonstrated that artificial miRNAs against HPSE might serve as an alterative mean of therapy to low HPSE expression and to block the adhesion, invasion, and metastasis of melanoma cells." (PMID 22719918, 2012). "In conclusion, our data suggests that artificial miRNA driven by the Pol II cytomegalovirus promoter may inhibit the expression of the HPSE protein and mRNA effectively, resulting in decreased invasion properties of melanoma cells in vitro and in vivo." (PMID 22719918, 2012). "Transfection of both nonmetastatic T lymphoma and melanoma cell lines with the heparanase gene caused both cell lines to become highly metastatic in vivo." (PMID 20445741, 2010). "Heparanase is preferentially expressed in both melanoma and carcinoma." (PMID 20445741, 2010). "Similarly, transcriptomic analysis has also been performed on heparanase-silenced melanoma cells." (PMID 34681753, 2021). "Based on in vitro and in vivo studies with melanoma models, Yang and colleagues proposed a model whereby heparanase could exert a dual function with a protumorigenic and a tumor-suppressive activity in the extracellular and the nuclear compartment, respectively." (PMID 30413079, 2018).
melanoma (continued). "Chemically modified heparins similarly demonstrated efficacy in inhibiting heparanase and reducing B16-BL6 melanoma metastatic activity to the lung in mice." (PMID 39594665, 2024). "Effective inhibition of heparanase-mediated degradation of heparan sulfate in the ECM and reduction in lung colonization by melanoma cells." (PMID 39594665, 2024). "As much, it was observed that specific inhibition of heparanase with heparin derivatives or selectin interactions in mouse models of MC-38 colon carcinoma and B16-BL6 melanoma reduces metastasis." (PMID 39108793, 2024). "FGF2 is a key regulator of melanoma angiogenesis and metastasis, and FGF2-induced melanoma angiogenesis is a heparan sulfate glycosaminoglycan chain that can be degraded by heparanase (HPSE) or HPSE (HS) regulation." (PMID 38393692, 2024). "In line with this, exogenous expression of the ECM-modifying enzyme heparanase can increase the tumor infiltration of chimeric-antigen receptor (CAR)–expressing αβ T cells, promoting tumor rejection in melanoma and neuroblastoma xenograft models." (PMID 37139603, 2023). "We found that melanoma MDA‐MB‐435s cells and MV3 cells expressed a remarkably high level of endogenous heparanase." (PMID 31044520, 2019). "In order to provide potential mechanistic insight through linkage of differential expression of pro‐apoptotic genes to melanoma cell apoptosis, we examined the expression of 28 pro‐apoptotic genes in MV3 cells after silencing HPSE using smartpool of siRNAs." (PMID 31044520, 2019). "Muparfostat inhibits heparanase with an IC50 of 7.9 nM and has previously been shown to suppress experimental lung metastases in a B16 melanoma model." (PMID 26039697, 2015). "Therefore, this study explored the effects of hinokitiol on the cancer-promoting pathway in mouse melanoma (B16F10) and breast (4T1) cancer cells, with emphasis on heparanase expression." (PMID 32132875, 2020). "Decreases in heparanase levels could also contribute to defects in metastases, as previously observed with BPTF KD melanoma tumors." (PMID 28969075, 2017). "Here, we show that heparanase is readily detected in most (88%) melanoma metastases, regardless of their anatomical site." (PMID 27732945, 2016). "Although the primary lesions of the same patients were not available to us, staining of un-matched primary melanoma sections for heparanase showed comparable staining intensities." (PMID 27732945, 2016). "Noteworthy, some nuclear staining of heparanase is retained in primary melanomas but is not detected in metastatic melanomas." (PMID 27732945, 2016). "Furthermore certain features found more often in melanoma cells in the brain compared to their extracranial counterparts, such as STAT3 (regulates a number of prosurvival genes) or heparanase (increases tumor invasiveness) could be exploited by the drug development community." (PMID 24455677, 2013). "However, despite promising results, clinical trials of heparanase inhibitors such as PI-88 and PG545 have not yet achieved significant success in melanoma monotherapy." (PMID 39594665, 2024).
diabetes (41 papers, 2011 to 2026). "Heparanase has been implicated in various experimental and human glomerular diseases associated with proteinuria, including diabetes and membranous nephropathy." (PMID 38426210, 2024). "Heparanase has gained interest as a druggable target in some diseases that are associated with chronic inflammation, such as cancer and diabetes." (PMID 38302978, 2024). "In contrast, and strikingly, 60% of HPSE-1-deficient hosts receiving HPSE-1-deficient T cells were diabetes free during the same period." (PMID 35563015, 2022). "Initially, it was found that HPSE-1 deficiency in either the donor T cells or the RIP-OVAhi recipient mice resulted in a small 2–3 day delay in diabetes onset." (PMID 35563015, 2022). "Heparanase has also been associated with inflammatory diseases such as atherosclerosis and diabetes." (PMID 31110966, 2019). "In diabetic nephropathy, cathepsin L-mediated activation of pro-heparanase into activated heparanase is associated with albuminuria and preceded the loss of synaptopodin in a streptozotocin-induced diabetes mouse model." (PMID 28491286, 2017). "Such an association is essential for the development of DN, as was proven by the observation that heparanase-deficient mice were protected against diabetes-induced proteinuria and renal damage." (PMID 28388547, 2017). "Increased urinary heparanase has also been implicated in several human proteinuric diseases such as diabetes, minimal change disease, membranous nephropathy and IgA nephropathy." (PMID 23028487, 2012). "Recent studies suggest a role for heparanase in several experimental and human glomerular diseases associated with proteinuria such as diabetes, minimal change disease, and membranous nephropathy." (PMID 23028487, 2012). "In diabetic patients, heparanase levels were significantly reduced following kidney transplantation implying that heparanase originates primarily from diabetes-associated kidney disease." (PMID 23028487, 2012). "Decreased urine heparanase levels in diabetic patients who underwent kidney transplantation suggest that urinary heparanase originates primarily from diabetes-associated kidney failure." (PMID 21364956, 2011). "Taken together, the results of this study support and further extend the causal involvement of heparanase in diabetes and the associated complications, and provide for the first time clinical association between blood glucose and heparanase secretion." (PMID 21364956, 2011). "Results presented in this study add another layer of evidence for the causal involvement of heparanase in diabetes." (PMID 21364956, 2011). "Furthermore, we have shown that protecting the eGlx with a novel polyvalent dendrimer which acts as a heparanase inhibitor, can prevent systemic microvascular permeability changes typically caused by diabetes." (PMID 38302978, 2024). "Studies have reported that the increase of blood glucose can lead to the upregulation of HPSE expression, and with the prolongation of diabetes, HPSE may cause more serious damage to islet function." (PMID 39296548, 2024). "Furthermore, experimental studies indicated that the encoded heparanase was engaged in diabetes initiation and progression." (PMID 35769078, 2022). "Thus, HS loss was prevented by a complete deficiency in HPSE-1 and was accompanied by a dramatic reduction in diabetes incidence." (PMID 35563015, 2022). "Interestingly, HPSE-1 deficiency alone in either the donor T cells or the recipient hosts delayed diabetes onset by 2–3 days but all animals became diabetic." (PMID 35563015, 2022). "Increased expression of HPSE is responsible for islet β cell autoimmunity in diabetes, but this gene may be associated with insulin resistance." (PMID 30678306, 2019). "The present study aims to investigate whether the ameliorative effect of XSF on diabetes-induced renal dysfunction associated with arginase and heparanase signaling." (PMID 30319431, 2018).